Y_RNA (Y RNA )
Gene: Miscellaneous RNA gene on chromosome 9 (130,120,806 to 130,120,912, forward strand). Ensembl gene ENSG00000223188.
Homologues: Orthologues: chimpanzee Y_RNA (86% identical), macaque Y_RNA (84% identical). Paralogues in human: Y_RNA (75% identical), Y_RNA (73% identical), Y_RNA (72% identical), RNY1 (71% identical), Y_RNA (71% identical), RNY1P11 (70% identical), Y_RNA (70% identical), RNY1P10 (69% identical), RNY1P14 (69% identical), RNY1P5 (69% identical), RNY1P9 (69% identical), Y_RNA (69% identical), and 83 more.